UAP1 (UDP-N-acetylglucosamine pyrophosphorylase 1)
Description:
Catalyzes the last step in biosynthesis of uridine diphosphate-N-acetylglucosamine (UDP-GlcNAc) by converting UTP and glucosamine 1-phosphate (GlcNAc-1-P) to the sugar nucleotide. Also converts UTP and galactosamine 1-phosphate (GalNAc-1-P) into uridine diphosphate-N-acetylgalactosamine (UDP-GalNAc). In addition to its role in metabolism, acts as a regulator of innate immunity in response to virus infection by mediating pyrophosphorylation of IRF3: catalyzes pyrophosphorylation of IRF3 phosphorylated at 'Ser-386' by TBK1, promoting IRF3 dimerization and activation, leading to type I interferon responses. [Isoform AGX1]: Isoform AGX1 has 2 to 3 times higher activity towards galactosamine 1-phosphate (GalNAc-1-P). [Isoform AGX1]: Isoform AGX2 has 8 times more activity towards glucosamine 1-phosphate (GlcNAc-1-P).
Synonyms: AGX; SPAG2; AGX1; AGX2
Tractability: Small molecule: a structure with a bound ligand is known; it has a high-quality binding pocket. Antibody: its Gene Ontology location is reachable by antibodies, with high confidence. PROTAC: ubiquitination databases record sites on it; its protein half-life has been measured.
Gene: Protein-coding gene on chromosome 1 (162,561,481 to 162,601,259, forward strand). Ensembl gene ENSG00000117143.
Subcellular location: Cytoplasm, cytosol
Subcellular location (Human Protein Atlas): Cytosol; Nucleoplasm; Plasma membrane
Pathways (Reactome):
Metabolism of proteins: Synthesis of UDP-N-acetyl-glucosamine
Gene Ontology:
Molecular function: identical protein binding; protein serine pyrophosphorylase activity; UDP-N-acetylgalactosamine diphosphorylase activity; UDP-N-acetylglucosamine diphosphorylase activity; transferase activity, transferring phosphorus-containing groups; uridylyltransferase activity
Biological process: antiviral innate immune response; positive regulation of type I interferon production; UDP-N-acetylglucosamine biosynthetic process
Cellular component: cytosol
Genetic constraint (gnomAD): Loss-of-function variants: 22 observed, 50.26 expected, observed/expected ratio (o/e) 0.44, 90% interval 0.31 to 0.62. The upper end of that interval is the gene's LOEUF score, 0.62, which puts it in group 2 of 6, group 1 being the genes least tolerant of losing a copy. Missense variants: 527 observed, 601.45 expected, observed/expected ratio (o/e) 0.88, 90% interval 0.81 to 0.94. Synonymous variants: 190 observed, 205.94 expected, observed/expected ratio (o/e) 0.92, 90% interval 0.82 to 1.04.
Homologues: Orthologues: chimpanzee UAP1 (99% identical), macaque UAP1 (99% identical), pig UAP1 (97% identical), dog UAP1 (96% identical), rabbit UAP1 (96% identical), guinea pig UAP1 (95% identical), mouse Uap1 (93% identical), rat Uap1 (93% identical), rat AABR07063082.1 (89% identical), zebrafish uap1 (73% identical), tropical clawed frog uap1 (72% identical), Drosophila melanogaster mmy (49% identical), and 1 more. Paralogues in human: UAP1L1 (56% identical), UGP2 (20% identical).
Diseases named in the same sentence as UAP1 in open-access papers:
UAP1 is named in the same sentence as 19 diseases in open-access papers, as found by Europe PMC text mining. Sharing a sentence is not in itself a finding about the gene and the disease. The quoted sentences say what the papers report.
prostate carcinoma (17 papers, 2013 to 2023). A carcinoma that arises from epithelial cells of the prostate gland. "Inhibiting expression of UAP1 sensitized prostate cancer cells to the inhibitor of N-linked glycosylation." (PMID 37838167, 2023). "Inhibition of UAP1 can specifically sensitize prostate cancer cells to the inhibitors of N-linked glycosylation." (PMID 34177996, 2021). "No UAP mutant was reported in these two higher model animals; however, UAP1 was found to be overexpressed in prostate cancer and protect against inhibitors of N-linked glycosylation, conferring a growth advantage." (PMID 34249055, 2021). "Moreover, their investigations further suggested that UAP1 could block the influence of N-linked glycosylation inhibitor on prostate cancer cells, which could be re-sensitized after silencing UAP1." (PMID 32310823, 2020). "UAP1 could protect prostate cancer cells against inhibitors of N-linked glycosylation." (PMID 31295943, 2019). "UAP1 expression is highly elevated in prostate cancer, where the increase in expression correlates with poor survival rate of patients with prostate cancer." (PMID 37838167, 2023). "In human, the expression level of UAP1 is positively correlated with the androgen receptor, which is a main driver of prostate cancer." (PMID 34177996, 2021). "Itkonen and coworkers reported that AGX1/UAP1 is over-expressed in prostate cancer cell lines, including PC3, and the over-expression is protective against inhibitors of N-linked glycosylation like tunicamycin (TM)." (PMID 32028604, 2020). "Given the important role of protein glycosylation in development of neoplastic disease, UAP1 was also found a critical regulator in prostate cancer." (PMID 32310823, 2020). "As for AGX1/UAP1, it has been proposed to be a therapeutic target for other diseases such as diabetes and prostate cancers." (PMID 32028604, 2020). "UAP1 plays an important role in energy metabolism and has been reported to be involved in prostate cancer pathogenesis." (PMID 32650368, 2020). "In their study, the authors showed that siRNA targeting AGX1/UAP1 gene led to increased sensitivity to tunicamycin treatment in cultured prostate cancer cells." (PMID 32028604, 2020). "A previous study in prostate cancer has shown the ability of UAP1 to protect cancer cells from endoplasmic reticulum stress and provide a growth advantage." (PMID 32650368, 2020). "Targeting UAP1 in prostate cancer cells reduced UDP-GlcNAc levels and blocks anchorage-independent growth." (PMID 31272438, 2019). "We found that two enzymes of the HBP, namely GFPT1 and UAP1 are up-regulated in prostate cancer cell lines." (PMID 23724116, 2013). "Besides, the mRNA and protein levels of GNPNAT1 and UAP1, as well as the ratio of the intermediate metabolites (GlcNAc-6-P/GlcN-6-P), are significantly elevated in prostate cancers, compared with benign prostatic hyperplasia." (PMID 36158580, 2022). "In studies of human prostate cancer cell lines, activation of the androgen receptor (AR) increases expression of UAP1 such that similar regulatory machinery may be driving its high expression in plethodontid sperm." (PMID 35281090, 2022). "UAP1 is overexpressed in prostate cancer cells and correlates negatively with Gleason score." (PMID 36275679, 2022). "Similarly, Itkonen and coworkers showed that siRNA targeting AGX1/UAP1 gene in PC3 cells led to increased sensitivity to tunicamycin treatment in cultured prostate cancer cells, as well as over 60% decrease in UGP-GlcNAc and UDP-GalNAc." (PMID 32028604, 2020). "For example, UAP1 is up-regulated in the early stages of prostate cancer." (PMID 31295943, 2019). "UAP1 and GCNT1 have been shown to be upregulated in PCa, and the amino-sugar conjugate, O-linked N-acetylglucosamine (O-GlcNAc) is significantly elevated in prostate cancer tissue." (PMID 26452038, 2015).
prostate carcinoma (continued). "Interestingly, the expression of both GFPT1 and UAP1 was increased by ∼50% in AR-positive prostate cancer cell lines LNCaP and VCaP compared to normal prostate cells PNT2 and RWPE-1." (PMID 23724116, 2013). "In addition, high UDP-GlcNAc levels correlate with increased UAP1 levels in prostate cancer cells." (PMID 33178836, 2020). "UAP1, the second rate-limiting enzyme in the final step of HBP, is also upregulated in prostate cancer and UBC." (PMID 36158580, 2022). "A recent study showed that prostate cancer contains higher levels of GNPNAT1 and UAP1 transcripts than benign tissue." (PMID 33178836, 2020). "Compared to benign tissue, prostate cancers contained elevated levels of GNPNAT1 and UAP1 transcripts, which was consistent with increased activity of HBP in matched tumor–benign pairs as detected when levels of UDP-GlcNAc were measured." (PMID 31272438, 2019). "In prostate cancer, GNPNAT1 and UAP1 are found to be highly expressed at the RNA and protein levels and high UDP-GlcNAc levels correlate with increased UAP1 protein levels in prostate cancer cells." (PMID 31272438, 2019). "Of 31 reciprocally-regulated glycosylation enzymes, a set of 8 (GALNT7, ST6GalNAc1, GCNT1, UAP1, PGM3, CSGALNACT1, ST6GAL1 and EDEM3) were significantly up-regulated in clinical prostate carcinoma." (PMID 27428423, 2016). "In prostate cancer, both GNPNAT1 and UAP1 are highly expressed at the RNA and protein levels." (PMID 33178836, 2020). "Similarly, UDP-N-Acetylglucosamine Pyrophosphorylase 1 (UAP1,the last enzyme in the HBP) is also overexpressed in prostate cancer tissue." (PMID 30893936, 2019). "Depletion of either UAP1 or PGM3 with two independent siRNAs significantly reduced cell viability of both LNCaP and CWR22Rv1 cells in comparison to cells treated with the control siRNA, consistent with expression of both these enzymes being important for prostate cancer cell survival." (PMID 27428423, 2016).
breast carcinoma (5 papers, 2019 to 2022). "The UAP1 activity can be inhibited by Fbxl17 through blocking the phosphorylation status of UAP1 in breast cancer." (PMID 36158580, 2022). "This was through its regulation of Uap1, which is expressed in many breast cancers and other cancer types." (PMID 31560077, 2020).
bladder cancer (3 papers, 2020 to 2023). "Elevated expression of UAP1 is also reported in bladder cancer, where its expression is critical for bladder cancer cell proliferation, migration, and invasion." (PMID 37838167, 2023). "SPAG2/UAP1 has been shown to be a promising therapeutic target for bladder cancer as well as lung adenocarcinoma." (PMID 35227274, 2022). "The silencing of UAP1 led to reduction in proliferation, invasion, colony formation and migration capability of bladder cancer cell lines." (PMID 32650368, 2020). "We evaluated the role of UDP-N-acetylhexosamine pyrophosphorylase (UAP1) in bladder cancer pathogenesis." (PMID 32650368, 2020). "Our data suggests that UAP1 could be a promising therapeutic target for aggressive urinary bladder cancer." (PMID 32650368, 2020). "Thus, our study reveals UAP1 as a promising therapeutic target for bladder cancer." (PMID 32650368, 2020). "We explored the role of UAP1 for the first time in bladder carcinoma, which was overexpressed in basal and non-type subtype cell lines." (PMID 32650368, 2020). "Furthermore, the functional characterization of UAP1 using siRNA-based silencing in non-type subtype BC cell lines resulted in a decrease in the cell proliferation, colony formation, invasion and migration properties of highly aggressive bladder cancer cell lines." (PMID 32650368, 2020). "In our data, we identified that UDP-N-acetylhexosamine pyrophosphorylase (UAP1) was overexpressed more than 2-fold in all the basal and non-type subtypes of bladder cancer cell lines." (PMID 32650368, 2020).
lung adenocarcinoma (3 papers, 2022). A carcinoma that arises from the lung and is characterized by the presence of malignant glandular epithelial cells. "In previous studies, the aminoacyl-tRNA biosynthesis pathway was an enrichment pathway for UAP1 expression-related genes in lung adenocarcinoma." (PMID 35586253, 2022). "UAP1 expression is upregulated in lung adenocarcinoma and correlates positively with larger tumor sizes and advanced TNM stages." (PMID 36275679, 2022).
breast tumors (2 papers, 2019 to 2020). "Kaplan–Meier analysis for these genes revealed that breast tumours with either low Fbxl17 expression, or high Uap1 expression were associated with poorer survival in patients." (PMID 31560077, 2020). "Among 200 hits, three genes (DEDD, ABCB10, and UAP1) are dysregulated (amplification and messenger RNA (mRNA) upregulation) in more than 40% of TNBC tumors and in 20% of all breast tumors examined." (PMID 31253784, 2019). "Interestingly, among the top dysregulated hits, a set of genes (DEDD, ABCB10, UAP1, KCNJ9, and PSAT1) are located close together on chromosome 1q23.3–42.1 and are co-amplified in >15% of breast tumors from 164 cancer genome studies." (PMID 31253784, 2019).
hepatocellular carcinoma (2 papers, 2023 to 2024). A malignant tumor that arises from hepatocytes. "UAPL1, a paralog of UAP1 that shares 59% sequence identity, is also upregulated in tumors such as hepatocellular carcinoma (HCC) and prostate and breast cancer." (PMID 37107691, 2023).
osteosarcoma (2 papers, 2022 to 2024). A usually aggressive malignant bone-forming mesenchymal neoplasm, predominantly affecting adolescents and young adults. "Four HBP-related genes (GFPT, GNPNAT, PGM3, and UAP1) can be used to guide immunologic and targeted therapies for osteosarcoma, with significant predictive value for osteosarcoma prognosis." (PMID 38915778, 2024). "IHC experiments suggested that UAP1 expression correlated significantly with the prognosis and metastasis of osteosarcoma patients." (PMID 36275679, 2022). "We constructed an HBP-related gene signature containing five key genes (GPI, PGM3, UAP1, OGT, MGEA5) which showed a remarkable prognostic value for predicting prognosis and can guide immunotherapy and targeted therapy for osteosarcoma." (PMID 36275679, 2022).
Infertility (1 paper, 2023). "Indeed, AGX1 (aka UAP1) is abundantly expressed in the testes of infertile males and implicated in antibody-mediated human infertility." (PMID 37107691, 2023).
Intellectual disability (1 paper, 2021). "A de novo mutation in UAP1 (NM_001324114:c.G685A:p.A229T) was reported in a patient with intellectual disability." (PMID 33098688, 2021).
renal carcinoma (1 paper, 2014). A carcinoma arising from the epithelium of the renal parenchyma or the renal pelvis. "By contrast, in renal carcinoma cells that do not produce N-GlcNAc2-modified proteins, GFPT1 and UAP1 were less activated (i.e.,<2-fold increase) by glucose deprivation over the same timescale." (PMID 24796485, 2014).
cancer (11 papers, 2015 to 2024). A tumor composed of atypical neoplastic, often pleomorphic cells that invade other tissues. "Cancer cells with higher UAP1 expression were more sensitive to cobimetinib, copanlisib, selumetinib and tamoxifen." (PMID 36275679, 2022). "We selected UDP-N-acetylhexosamine pyrophosphorylase (UAP1) as a candidate molecule to study the functional implication in BC, based on its function and association with cancer pathogenesis." (PMID 32650368, 2020). "Silencing of UAP1 inhibited the growth and colony formation of cancer cells." (PMID 36845730, 2023). "Indeed, both UGP2 and AGX1/UAP1 have been shown to play a role in cancer growth." (PMID 32028604, 2020). "In our study, we found that UAP1 gene is amplified in ∼16% of UBC patients in TCGA-BLCA dataset, suggesting another molecular mechanism for the increased UAP1 activity during cancer development." (PMID 36158580, 2022). "In some datasets where GFAT expression was not significantly increased, one of GNPNAT1, PGM3, or UAP1 was highly expressed in cancer tissues." (PMID 31645543, 2019). "The roles of UAP1, HEATR2, and MBOAT7 in cancer remains unclear." (PMID 25577646, 2015).
tumor (11 papers, 2011 to 2024). "In particular, this included genes involved in secretory pathways, lipid and sugar metabolism (such as, UGDH, SORD, GLUD1, ELOVL5, ASCL3, UAP1), but also genes implicated in tumor progression and metastasis with functions in cell survival, proliferation and adhesion (EHF, ELL2, TPD52, MAFB, SGK)." (PMID 21829708, 2011). "What’s more, UAP1 protects tumor cells from ER stress, thereby conferring advantages for tumor growth." (PMID 36275679, 2022). "Depletion of UAP1 in these cells re-sensitized them to inhibitors of N-linked glycosylation, thus underscoring the role of UAP1 in generating UDP-GlcNAc that is critical for tumor growth." (PMID 37107691, 2023). "Since the silencing of UAP1 reduces both the cell proliferation and colony forming ability of non-type subtype BC cells, we decided to explore whether UAP1 has any role in tumor cell motility." (PMID 32650368, 2020). "In PDAC, we revealed a slight increase of GNPNAT1 and UAP1 expression and a significant overexpression of GFAT1 in tumor tissues compared with normal counterparts." (PMID 32149084, 2020). "Similarly, another independent GSE3167 dataset also displayed the increased mRNA expression levels of GFPT1, PGM3, and UAP1 and the decreased GFPT2 level in tumor tissues, while the data of GNPNAT1 gene were not available in this dataset." (PMID 36158580, 2022).
UAP1 also shares sentences with these, for which no sentence is quoted: anaplastic thyroid cancer (1 paper); Autoimmunity (1); benign prostatic hyperplasia (1); cyst (1); developmental delay (1); diabetes (1); infection (1).